ACYP1 (acylphosphatase 1)
Synonyms: ACYPE
Tractability: PROTAC: ubiquitination databases record sites on it; its protein half-life has been measured.
Gene: Protein-coding gene on chromosome 14 (75,053,221 to 75,069,483, reverse strand). Ensembl gene ENSG00000119640.
Subcellular location (Human Protein Atlas): Cytosol; Nucleoplasm
Gene Ontology:
Molecular function: acylphosphatase activity
Biological process: phosphate-containing compound metabolic process
Genetic constraint (gnomAD): Loss-of-function variants: 8 observed, 11.08 expected, observed/expected ratio (o/e) 0.72, 90% interval 0.42 to 1.3. The upper end of that interval is the gene's LOEUF score, 1.3, which puts it in group 5 of 6, group 1 being the genes least tolerant of losing a copy. Missense variants: 93 observed, 123.74 expected, observed/expected ratio (o/e) 0.75, 90% interval 0.63 to 0.89. Synonymous variants: 38 observed, 43.39 expected, observed/expected ratio (o/e) 0.88, 90% interval 0.68 to 1.15.
Homologues: Orthologues: chimpanzee ACYP1 (100% identical), Drosophila melanogaster CG34161 (43% identical), Drosophila melanogaster Acyp2 (41% identical), Drosophila melanogaster CG18371 (41% identical), Drosophila melanogaster Acyp (39% identical), Drosophila melanogaster CG11052 (36% identical). Paralogues in human: ACYP2 (57% identical).
Diseases named in the same sentence as ACYP1 in open-access papers:
ACYP1 is named in the same sentence as 21 diseases in open-access papers, as found by Europe PMC text mining. Sharing a sentence is not in itself a finding about the gene and the disease. The quoted sentences say what the papers report.
hepatocellular carcinoma (3 papers, 2022 to 2025). A malignant tumor that arises from hepatocytes. "For example, targeting ACYP1-mediated glycolysis can reverse lenvatinib resistance and limit the progression of hepatocellular carcinoma." (PMID 40756987, 2025). "Then, we extended our studies to the subcutaneous implantation tumor model of Hep1-6 (mouse hepatoma cells) to explore the potential roles of ACYP1 in tumor progression and the TME." (PMID 35586489, 2022). "For glycolysis in cancers, targeting ACYP1-mediated glycolysis could reverse lenvatinib resistance and restrict hepatocellular carcinoma progression." (PMID 39990672, 2025).
breast carcinoma (2 papers, 2022 to 2025). "Moreover, reduced expression of ACYP1 was found in brain cancer, breast cancer, head and neck cancer, and other cancers, while TCGA database analysis results via TIMER were not the same." (PMID 35586489, 2022). "Decreased expression of ACYP1 was found in the head and neck cancer, breast cancer, etc.." (PMID 35586489, 2022). "ACYP1 regulates glycolytic processes and is implicated in tumor growth, invasion, and resistance to apoptosis in liver cancer, while MFF plays a central role in mitochondrial fission and is implicated in lung, colon, and breast cancers by regulating cell proliferation, apoptosis, and invasion." (PMID 40503897, 2025).
liver cancer (2 papers, 2022 to 2025). An epithelial or non-epithelial malignant neoplasm that arises from the liver. "Several studies have shown that ACYP1 is a metabolism-related gene involved in gastric and liver cancer progression." (PMID 35586489, 2022). "As a metabolism-related gene with prognostic value in gastric cancer and liver cancer, ACYP1 may become an important candidate target for metabolic therapy." (PMID 35586489, 2022). "ACYP1 is considered to be a metabolism-related gene used to predict the prognosis of patients with gastric and liver cancer and may become an important candidate target for metabolic therapy." (PMID 35586489, 2022).
cholangiocarcinoma (1 paper, 2022). A carcinoma that arises from the intrahepatic biliary tree (intrahepatic cholangiocarcinoma) or from the junction, or adjacent to the junction, of the right and left hepatic ducts (hilar cholangiocarcinoma). "A recent study revealed that the high expression of ACYP1 was significantly associated with a poor prognosis for cholangiocarcinoma (CHOL) patients, which may be related to the effect of ACYP1 on cell viability and apoptosis." (PMID 35586489, 2022).
colorectal cancer (1 paper, 2022). A primary or metastatic malignant neoplasm that affects the colon or rectum. "For colorectal cancer, ACYP1 was only a favorable prognostic factor in terms of OS, but not RFS in READ (HR=0.39, p=0.029)." (PMID 35586489, 2022).
head and neck cancer (1 paper, 2022). A primary or metastatic malignant neoplasm affecting the head and neck. "Interestingly, in lung cancer and head and neck cancers, ACYP1 played a protective role." (PMID 35586489, 2022).
Hepatitis (1 paper, 2022). Inflammation of the liver. "Our study revealed that ACYP1 plays an adverse role in LIHC patients, although its implication may vary depending on clinical characteristics such as sex, race, tumor stage, tumor grade, vascular invasion, alcohol consumption, and hepatitis status according to multifactor regression analysis." (PMID 35586489, 2022).
cancer (4 papers, 2020 to 2025). A tumor composed of atypical neoplastic, often pleomorphic cells that invade other tissues. "Of note, high expression of ACYP1 indicated poor prognosis across cancers in a total of 9497 patients, and OS and DFS were significantly different (OS: HR= 1.1, P = 0.039; DFS: HR= 1.1, P = 0.049)." (PMID 35586489, 2022). "Based on the difference in expression across cancers, the prognostic value of ACYP1 was predicted in different databases." (PMID 35586489, 2022). "In conclusion, we demonstrated for the first time the role of ACYP1 in predicting prognosis, and the TME, and associated pathways across cancers." (PMID 35586489, 2022). "In the UALCAN database, ACYP1 expression in cancer stage, patient age, tumor grade, and histological subtypes was significantly different." (PMID 35586489, 2022). "The relationships between ACYP1 expression levels and prognosis for each type of cancer were explored using Kaplan–Meier Plotter." (PMID 35586489, 2022). "ACYP1 expression was significantly higher in most cancers than in their respective adjacent normal tissues." (PMID 35586489, 2022). "First, in Oncomine, ACYP1 expression was higher in a variety of cancer groups versus their corresponding normal control groups." (PMID 35586489, 2022). "Our study aimed to understand the ACYP1 expression signature and prognostic value across cancers and investigate immune infiltration patterns in liver hepatocellular carcinoma (LIHC) and verify them in LIHC samples." (PMID 35586489, 2022). "In this study, we analyzed the expression levels of ACYP1 and its prognostic value across cancers using multiple databases." (PMID 35586489, 2022). "The results from the Wurmbach mixed liver dataset showed that ACYP1 expression varied significantly by cancer type, grade, hepatitis virus infection status, and vascular invasion." (PMID 35586489, 2022). "Fatty acid metabolism and ACYP1: Cancer cells must rewire cellular metabolism to satisfy the demands of growth and proliferation." (PMID 33188160, 2020). "We first analyzed the overall effect of ACYP1 on all 33 cancer types." (PMID 35586489, 2022). "First, we analyzed ACYP1 mRNA expression levels in Oncomine across cancers." (PMID 35586489, 2022). "We further explored the effect of ACYP1 on the prognosis of various cancers." (PMID 35586489, 2022). "We then analyzed the role of ACYP1 in each of the cancer types." (PMID 35586489, 2022). "The TIMER database was used to evaluate ACYP1 expression across cancers." (PMID 35586489, 2022). "Transcriptional expression profiles of ACYP1 across cancers were analyzed using Oncomine and TIMER." (PMID 35586489, 2022). "ACYP1 expression was higher in a variety of cancer groups than in the respective normal tissues." (PMID 35586489, 2022). "A number of these genes, including ACYP1, MFF, SLC44A1, and HFE, promote cancer development by regulating metabolic pathways." (PMID 40503897, 2025). "This study was focused on the prognostic value across cancers, signaling pathways and the TME in LIHC by analyzing the expression of ACYP1." (PMID 35586489, 2022).
tumor (4 papers, 2022 to 2025). "We validated ACYP1 expression, prognostic value, and association with immune cells in tumor tissues by immunohistochemistry and flow cytometry." (PMID 35586489, 2022). "Combinatorial targeting of ACYP1 alongside lenvatinib has been demonstrated to substantially mitigate lenvatinib resistance and impede tumor progression." (PMID 39403606, 2024). "The tumor in the ACYP1 overexpression group were significantly larger and weighted more than those in the vector group." (PMID 35586489, 2022). "The results showed that high ACYP1 expression was an adverse prognostic factor for five of these tumor types, including breast, colorectal, brain, soft tissue cancers and skin." (PMID 35586489, 2022). "In a mouse subcutaneous tumor model, high expression of ACYP1 was closely related to tumor progression." (PMID 35586489, 2022). "Overall, ACYP1 has potential as a pancancer prognostic marker from the perspective of tumor immunology and provides a novel target for the treatment of LIHC." (PMID 35586489, 2022). "The results showed that ACYP1 was an enzyme in the progress of glycolysis and promoted tumor progression via participating in the glycolysis and immunosuppression." (PMID 35586489, 2022). "Mouse subcutaneous tumors with ACYP1 overexpression exhibited significantly accelerated tumor progression with increased aggregation of CD4+ T cells." (PMID 35586489, 2022). "Remarkably, ACYP1 overexpression significantly accelerated tumor growth under the skin." (PMID 35586489, 2022). "High expression of ACYP1 correlated with a poor prognosis in most tumor types, especially in LIHC." (PMID 35586489, 2022). "Acylphosphatase 1 (ACYP1), a small cytoplasmic protein, has been shown to boost the metabolic capacity of tumor cells by promoting glycolysis, thereby enhancing tumor proliferation, invasion, and migration." (PMID 40612869, 2025). "This suggests the potential for developing metabolism-targeted oncolytic viruses that preferentially infect cells with high ACYP1 expression, further improving the specificity of the virus in HCC and enhancing the tumor killing ability." (PMID 40612869, 2025). "ACYP1 exacerbates the Warburg effect through activation of the Myc/LDHA axis, contributing to its tumor-supportive effects." (PMID 39403606, 2024). "In a study investigating the potential of targeting ACYP1 in combination with levatinib, a first-line therapy for advanced HCC, it was found that this dual targeting significantly increased HCC sensitivity to levatinib and slowed tumor progression." (PMID 40612869, 2025). "The results showed that male sex, Asian race, stage I tumor, stage, grade, AJCC T stage, microvascular invasion, history of alcohol consumption, and hepatitis virus infection were closely related to high expression of ACYP1, which indicates a worse OS in LIHC." (PMID 35586489, 2022). "The higher expression of ACYP1 may be closely related to negative immunity in the tumor itself." (PMID 35586489, 2022).
ACYP1 also shares sentences with these, for which no sentence is quoted: brain cancer (1 paper); cardiomyopathies (1); diffuse large B-cell lymphoma (1); gastric cancer (1); gastrointestinal stromal tumor (1); lung carcinoma (1); lymphoid neoplasm (1); pancreatic adenocarcinoma (1); skin cutaneous melanoma (1); thymoma (1); uterine carcinosarcoma (1); vitiligo (1).